CD163 (CD163 molecule)
Diseases named in the same sentence as CD163 in open-access papers (continued):
Sharing a sentence is not in itself a finding about the gene and the disease.
cancer (continued). "qRT-PCR analysis revealed that TAMs cocultured with MMP28-knockdown cancer cells presented upregulated CD86 expression and downregulated CD163 expression." (PMID 39972459, 2025). "Conversely, alternatively activated (M2) macrophages identified by markers such as CD163 and CD206, frequently infiltrate malignant tumors, driving cancer progression." (PMID 39972459, 2025). "The pro-tumorigenic role of CD163+ M2-like MPs has previously been described by several studies of CRC including CRC mouse models, and other types of cancer." (PMID 40136704, 2025). "Here we show that MPNST cells secrete factors that lead to acquisition of M2 markers (CD206, CD163, MGL-1, MMP-9, VEGF-A, ARG and GS) by macrophages, enabling their induction of cancer cell growth and motility and of endothelial cell angiogenesis." (PMID 40877908, 2025). "Increased amounts of specific TAM subsets identified by CD163, CD206, stabilin-1, and TREM2 biomarkers correlate with both hematogenous and lymphatic metastasis in all cancer types studied." (PMID 39516356, 2024). "Cluster 25 (CD163+ApoE+) macrophages expressed S100A4 and S100A10, while Cluster 18 (ApoE+ki67+) cancer cells expressed high levels of ApoE, Ki-67, and vimentin." (PMID 39695088, 2024). "The distance of CD163 TAM from cancer cells and a higher average number of them in close contact with cancer cells were independent predictors of unfavorable prognosis." (PMID 38893266, 2024). "Within large spheroids, TAMs displaying M2-polarization markers (including CD163, CD206 and arginase 1) are located in the center of spheroids and surrounded by EGFR+ cancer cells." (PMID 39513610, 2024). "Another study demonstrated that high CD163+ TAM numbers were related with increased proliferation and poor differentiation of cancer cells and ER negativity." (PMID 39044824, 2024). "Among these cell type markers of cell clusters, cancer cell cluster specifically expressed keratin 19 (KRT19) and CEA cell adhesion molecule 1 (CEACAM1), and TAM cluster expressed CD68, CD163, and complement C1q C chain (C1QC)." (PMID 38302412, 2024). "Correlation analysis with immunohistochemistry findings showed that the degrees of CD4 + and CD163 + cell infiltration and IL-6 and MMP-11 expression were correlated with cancer imaging features on PET/CT." (PMID 38627864, 2024). "Forced MALAT1 expression in cancer cells and xenograft models led to increased cell growth, invasiveness, and movement, along with higher levels of MCP-1, CD68, CD163, CD206, and KI67." (PMID 38791954, 2024). "Regarding the expression levels of CD68 as a M1-TAM marker in carcinomas and prognosis, it has been reported that the low expression of CD68 and CD163 in classical Hodgkin lymphoma indicates a better prognosis." (PMID 39199574, 2024). "As CD163 is used to broadly interpret immune presence in tissue, the differences in immune infiltration found in our molecular studies may additionally warrant use of other stains to assess myeloid polarization and its influence on T-cell mediated immune control and cancer growth." (PMID 38049893, 2023). "CD163+CD206+ macrophages have been classified as belonging to the M2-subtype, which favors tumorigenesis and cancer progression." (PMID 36922898, 2023). "We then aimed to investigate the prognostic value of COMP expression levels in CRC tumors corrected for PD-L1 expression by immune cells and cancer cells, and the different markers of immune cells populations (CD3+, CD8+, FoxP3+, CD68+, CD56+, and CD163+)." (PMID 37207219, 2023). "We have evaluated 16 studies that used macrophage/monocyte markers in PMDs and cancer using antibodies against CD68 (pan-MΦ), CD86, CD80 (both M1-MΦ), CD163 and CD204 (both M2-MΦ), and CD14 (monocyte/macrophage marker)." (PMID 37190121, 2023). "For patients with more advanced cancer (stages IIB and III), the MH index between CD8+ and CD163+ cells were significantly correlated with survival (DFS, P=0.0161; OS, P=0.0190)." (PMID 37090736, 2023).
cancer (continued). "Double immunohistochemical (IHC) analysis of CD163 and pSTAT3 expression showed that STAT3 activation was induced in cancer cells located near TAMs." (PMID 36961655, 2023). "In summary, our study implies that ZIC2 induces M2 TAM polarization, at least in part through regulation of JUNB/MCSF and that ZIC2, JUNB, and CD163 can be utilized as prognostic markers for NPC and as therapeutic targets for cancer immunotherapy." (PMID 37479694, 2023). "GSCALite was utilized to identify the SNV frequency of all 6 genes (CD68, MRC1, CD8A, CD8B, CD163, and CLEC5A) in various cancers." (PMID 35979347, 2022). "Here, we determined the prevalence of CD163+ and MAC387+ TAMs in the cancer tissues of HCMV+ compared to HCMV- IBC patients." (PMID 35847899, 2022). "Meanwhile, we took the orthotopic cancer tissue for IHC analysis, which indicated a decrease in M1 (CD86) and M2 macrophage markers (CD163 and CD206)." (PMID 36612128, 2022). "To analyze the intratumoral TME, we quantitatively compared iTAM cell counts using the CD68, CD163, PD-L1, CD20, and pan-CK markers in the three cancer subtypes." (PMID 36362023, 2022). "Next, we evaluated the correlation between the DNA methylation and mRNA expression of CLEC5A and immune-related gene (MRC1, CD163, CD8A, CD8B, CD68) in pan-cancer." (PMID 35979347, 2022). "Supporting this cancer stem cell theory, new evidence suggests that GBM cells often show overexpression of common neural progenitor-cell markers such as nestin, CD133 and CD163." (PMID 35269752, 2022). "The pie chart showed that the heterozygous CNVs of all 6 genes (CD68, MRC1, CD8A, CD8B, CD163, and CLEC5A) was more frequent in various cancers." (PMID 35979347, 2022). "SpatialVizScore generated immune cell infiltration maps using several cancer markers (pan-keratin & e-cadherin), stromal markers (SMA & collagen 1), and immune markers (CD8ɑ, CD68, CD163, CD206, and HLA-DR)." (PMID 36050391, 2022). "Meanwhile, multiplex immunofluorescence staining was used to verify the expression of CD147 on macrophages and M2 macrophages in these cancers, which CD147 was mainly expressed on CD163+ M2 macrophages in BLCA, LSCC, CESC, PSCC, TGCT, and PRAD." (PMID 35464411, 2022). "M2 macrophage markers such as CD163, CD68, CD206, and CD204 are TAM markers that are widely used to assess cancer progression." (PMID 36077342, 2022). "We stained stromal areas near cancer cells for panmacrophage (CD68), M2 macrophage (CD163), immune modification (PD-L1), and pancytokeratin (CK) markers using a multicolored immunohistochemical method." (PMID 36362023, 2022). "Even though CD68, CD163, and CD204 have been widely used to assess the severity and outcome of human cancers, opinion on what constitutes the definitive TAM marker remains controversial." (PMID 36077342, 2022). "Cells with double positivity (α-SMA+ CD163+) ranged from 10.2% to 13.6% of all α-SMA+ cells in these cancer types, which is consistent with our pan-cancer single-cell analysis and a previous report in pancreatic cancer." (PMID 36333338, 2022). "Epithelial cell adhesion molecule (EpCAM)+ cancer cells (PD-L1− or T cell immunoglobulin mucin-3, TIM-3−), both PD-1 or TIM-3 positive CD8+ T cells, and CD14+CD68+CD163+TIM-3+ macrophages increased from the MPE1st to MPE2nd." (PMID 36293034, 2022). "These macrophages are recruited and polarized into a pro-tumoral phenotype (upregulation of CD206, CD163 and CD209) by CSF-1, CXCL2, VEGFA and CCL18 produced by cancer cells." (PMID 35309358, 2022). "The carcinoma tissues and adjacent tissues were collected from 104 LSCC cases, and the positive relationship between CD163-/CD206-M2 macrophage infiltration and clinical phase, lymph node spreading and pathological phase in LSCC was observed." (PMID 36424539, 2022).
cancer (continued). "Because both analyses showed that OLFML2B was positively correlated with macrophage content, we input cancer-related macrophage markers into the web tool “CellMarker” and obtained experimentally verified markers: CD14, CD68, CD163, CSF1R, ITGAM, and MRC1." (PMID 34868901, 2021). "Actually, these CD163 and CHI3L2 have been suggested as prognostic biomarkers in other types of cancers." (PMID 34395626, 2021). "Our study suggests that CD163+ TAMs further create an optimal TME for growth and invasion of cancer cells when evasion of immunoreactions by T and B TILs occurs." (PMID 34089486, 2021). "Finally, cell fusion of macrophages and cancer cells might skew CD163 quantification." (PMID 32752088, 2020). "Therefore, specific targeting of CD163+ macrophages may contribute to current cancer therapy." (PMID 32752088, 2020). "Coexpression of cancer-related markers, such as cytokeratins or EpCAM, and hematopoietic lineage markers, such as CD45 and CD163, is another strategy to identify putative TN-hybrid cells in human cancers." (PMID 30736482, 2019). "Immunostaining of M2-macrophage-specific antigen CD163 in cancer cells and MI were evaluated, together with ER, PR, HER2, and Ki-67-expression in cancer cells." (PMID 30915533, 2019). "CD68 and CD163 (TAM markers) were observed to be correlated with lymph node status and with several cancer stem cell markers such as SOX2 (sex determining region Y) and ALDH1 (aldehyde dehydrogenase 1)." (PMID 29976244, 2018). "Across cancer types, percentages of single positive CD68+ and CD163+ pixels, ranged from 6.5 to 62.7%, while CD11b+ and CD11c+ single pixels ranged from 0.65 to 11%." (PMID 30619287, 2018). "Elevation of CD163, PD-L1 and IL-10 expression on CD14+ monocytes from PBMCs of cancer patients was observed as compared to those from healthy donors." (PMID 30563569, 2018). "Therefore, our results suggest that both regulatory macrophages and dexa-tolDC might be triggering similar tolerogenic mechanisms, probably through the STAT3 and Wnt5a signaling pathway, as its interaction with CD163 has already been reported in cancer studies." (PMID 30297862, 2018). "GFP+/CD163+/CD45+ cells were defined as hybrids and GFP+/CD163–/CD45– cells were defined as MCF-7 cancer cells." (PMID 28881654, 2017). "Cancer tissue had increased immune cell infiltration with recruitment of CD163+ (M2 macrophage), CD25+ (regulatory T lymphocyte), and CD4+ (T helper) cells compared to non-cancer tissue." (PMID 26964534, 2016). "As experimental controls MCF-7 cancer cells and macrophages co-cultured for three days in the same medium in a transwell chamber system were also analyzed by flow cytometry for GFP, CD163 and CD45 expression." (PMID 26585897, 2015). "Macrophage traits, represented by CD163 and CD45 expression in cancer cells, are due to fusion between cancer cells and macrophages, and cannot be explained by cellular interaction between these cells." (PMID 26585897, 2015). "MCF-7 cancer cells obtained CD163 and CD45 expression only by hybridization between MCF-7 cancer cells and macrophages." (PMID 26585897, 2015). "In the current study, cancer cell-conditioned medium and IL-10 induced higher expression levels of CD14, CD16 and CD163 with normal DC markers, including CD11c and CD209." (PMID 25013476, 2014). "The positive expression rates of CD163+ and CD68+ were 68% and 78% respectively in cancer tissues compared to 4% and 6% in the adjacent cancer tissues." (PMID 25144454, 2014). "Under co-culture conditions the cancer cells express the macrophages-specific antigens, e.g. CD14, CD64, CD163, CSF1R." (PMID 22353646, 2012). "The real-time qPCR confirmed the CCL2, CCL3, CD163, CSF1R, MMP9, HIF1, VEGF-C up-regulation in cancer cells grown as a co-culture with macrophages." (PMID 22353646, 2012).
cancer (continued). "With the use of these well recognized markers, it appeared that ATC tissue harbored only three types of cells: NOX2+ P22phox+ CD163+ CD68+ CD34− macrophages; NOX2− P22phox− CD163− CD68− CD34− cancer cells and NOX2− CD163− CD68− CD34+ blood vessel endothelium." (PMID 21811634, 2011). "We performed co- immunostainings on controls and on malignant endometrial tissues (G2 carcinoma) with antibodies for CD14 and CD163." (PMID 18775079, 2008). "Moreover, spatial transcriptional data obtained from the STOmics DB database revealed a spatial overlap between SUSD3 expression and markers of M2 macrophages, namely CD163 and CD68, within HINSC cancer tissues." (PMID 40191190, 2025). "Conversely, the incubation with the CM from LpOC01-SN precured CRC cells led to a notable decrease in CD206 and CD163 expression in macrophages, supporting that Lactiplantibacillus plantarum OC01 metabolites modified the TME by altering the cancer cell secretome." (PMID 40002754, 2025). "The density of TAMs decreased with each progressive cancer stage, and locoregional cancers (stage I–III) had a higher density of CD68+ TAMs than cancers with distant metastasis (stage IV) irrespective of CD163 expression." (PMID 38407700, 2024). "The number and the area of CD163+ macrophages in all 17 patients with PM were higher than non-cancer part." (PMID 38745748, 2024). "Interestingly, CD163 is a novel target gene of STAT3 and has been proposed as a therapeutic target in cancer." (PMID 38592450, 2024). "Overall, CD163 in tumors has been widely used as a TAM marker, especially of the M2 orientation, and its high expression levels have been correlated with poor prognosis, metastasis, and overall survival in various cancers." (PMID 39451197, 2024). "Accumulating evidence has shown that the serum lipids level of cancer patients was correlated with many immune biomarkers, including CD3, CD8, CD163, and iNOS,16 which could promote the function of effector T cells and potentiate an antitumor program." (PMID 37409613, 2023). "Both CD163 and CD4 + CXCR5 can be regarded as prognostic predictors for CRC patients to facilitate the evaluation of cancer prognosis and TME status, thereby optimizing individualized treatment plans and improving cancer patient survival." (PMID 36859111, 2023). "The high expression levels of ZIC2 and JUNB were positively correlated and linked to a poor outcomes in NPC patients, implying that ZIC2, JUNB, and CD163 could be utilized as prognostic markers for NPC and as therapeutic targets for cancer immunotherapy." (PMID 37479694, 2023). "In these hemorrhagic regions, we found an increased Cd68 signal, confirming macrophage infiltration, superimposed by upregulated expression of Hmox1 and Arg1, the latter of which is the archetypal marker for procancerous and immunosuppressive TAMs in mice, similar to CD163 and SPP1 in human cancers." (PMID 38060331, 2023). "In cancer patients, number of TAM-expressed SRs (CD204, MARCO, CD68, LOX-1, Dectin-1, CD206, CXCL16, Stabilin-1, CD163, and RAGE) associates with negative and more sever prognosis." (PMID 36686729, 2022). "Based on our findings, we concluded that EMR1 upregulation in cancer cells is regulated by TAM and has a significant relationship with lymph node metastasis, and the combined EMR1-TC+CD68+CD163+ expression can be used as a prognostic indicator in patients with CRC." (PMID 36551877, 2022). "The CD163/IL‐6/Stat3 pathway is suggested to be critical in protumor TAMs, however, macrophage‐mediated cancer cell proliferation was not affected by anti‐IL‐6R antibody (unpublished data)." (PMID 35132816, 2022). "Because PD-L1-negative EpCAM+ cancer cells, low PD-1 expressed CD8+T cells, and remarkably increased CD14+CD68+CD163+TIM-3+ macrophages were observed in MPE with disease progression, TIM-3 blockade therapy might be applicable to treatment." (PMID 36293034, 2022).
cancer (continued). "Thus, the DNA methylation differences of CLEC5A and immune-related gene (MRC1, CD163, CD8A, CD8B, CD68) between tumors and normal tissues in various cancers were evaluated with the GSCALite platform." (PMID 35979347, 2022). "Although the expression levels of CD163, CD204, and CD206 were significantly upregulated in cancer tissues compared to paratumor tissues, CD163, CD204, and CD206 were not expressed at high levels in TAMs than other markers." (PMID 35725444, 2022). "Thus, we determined the incidence of CD14+ monocytes, and CD68+, CD163+ and MAC387+ TAMs in the cancer tissues of HCMV+ IBC patients." (PMID 35847899, 2022). "Several cancers showed positive correlations between JMJD8 and CD163 intensity, such as LGG." (PMID 35898493, 2022). "Particularly, CD163+ TAMs have been observed to secrete IL-6, which, upon binding of IL-6 receptor (IL6R) on the cancer cell surface, phosphorylate STAT3 (pSTAT3) that translocated to the nucleus and regulates the expression of varying microRNAs, including miR-506-3p, which promotes EMT." (PMID 36555840, 2022). "Parallel with our results, an increased expression of CD163 was shown to be a significant negative prognosticator for patients with cancers of the breast, skin, head, and neck, among others." (PMID 34298638, 2021). "Recently, we reported that the number of intraepithelial CD163-positive macrophages of the TL with cancer invasion is higher compared to those of TL with no cancer invasion." (PMID 34178651, 2021). "However, our data highlight the pronounced heterogeneity of BTK protein expression in distinct cell types including cancer stem-like cells (SOX2), TAMs (CD163) and microglia (CD68)." (PMID 34645618, 2021). "Thus, our study suggests that CD163+ TAMs further create an optimal TME for growth and invasion of cancer cells when evasion of immunoreactions by T and B TILs occurs." (PMID 34089486, 2021). "The CD163 staining pattern showed that the less nonspecific staining of carcinoma cells and other inflammatory factors in a cleaner background than CD68." (PMID 33928349, 2021). "STAT3 correlated with CD68 and CD163, meaning that STAT3 might correlate with M2 macrophage to regulate cancer development." (PMID 32486001, 2020). "However, in cancer tissue samples with strong expression of TGM2 in GC cells, 73.3% (22/30) of the samples showed high expression of the macrophage marker CD163 (Fisher's exact test, P = 0.006)." (PMID 32467608, 2020). "Thus, the numbers of CD68+ macrophages, as well as the numbers of macrophages positive for M2 markers (CD163 and CD204) in borderline and malignant tumors were significantly higher in both serous and mucinous ovarian tumors than in benign tumors." (PMID 33194645, 2020). "To evaluate how CPEB3 in CRC cells may inhibit M2-like TAM polarization, we first assessed the expression of CPEB3, CD86 and CD163 in 82 pairs of CRC tissues and adjacent non-cancer tissues using qRT-PCR." (PMID 32653013, 2020). "Regarding CD163, which identifies M2-like macrophages, its positivity was significantly lower in the PTA than in the TC (p = 0.02) in each sample tested, showing a gradient that indicates a consistent engagement of these cells by the cancer." (PMID 32899203, 2020). "In accordance with ZEB1 deposition, considerable CD163+ TAMs infiltrated the stroma surrounding the hypoxic cancer cell islets but not the normoxic regions." (PMID 31263103, 2019). "PET imaging of a 68Ga labeled antibody for CD163 has been performed in rats with collagen-induced arthritis 67, but to our knowledge not yet in cancer models." (PMID 31695797, 2019).